RRM1 (ribonucleotide reductase catalytic subunit M1)
Diseases named in the same sentence as RRM1 in open-access papers (continued):
Sharing a sentence is not in itself a finding about the gene and the disease.
multiple myeloma (8 papers, 2017 to 2025). "Multiple myeloma cells were shown to be dependent on RRM1 and high RRM1 RNA expression is associated with an adverse outcome." (PMID 35197447, 2022). "In line with this, we found RRM1 overexpression to reduce IMiD sensitivity in multiple myeloma cells." (PMID 35197447, 2022). "In aggregate, these data imply that high CDK6 and RRM1 expression selectively reduce IMiD sensitivity in multiple myeloma cell lines." (PMID 35197447, 2022). "These analyses reveal a CDK6-governed protein resistance signature that includes myeloma high-risk factors such as TRIP13 and RRM1." (PMID 35197447, 2022). "Our gMCS computational framework is applied to evaluate the lethality of ribonucleotide reductase catalytic subunit M1 (RRM1) in multiple myeloma (MM), a hematological cancer that remains for the most part an incurable disease." (PMID 28878380, 2017). "Here, the authors present an approach to identifying such interactions by finding genetic minimal cut sets (gMCSs) that block cancer proliferation, and apply it to study the lethality of RRM1 inhibition in multiple myeloma." (PMID 28878380, 2017). "We present a computational and experimental study of the effect of RRM1 inhibition in four multiple myeloma cell lines." (PMID 28878380, 2017). "Our genetic minimal cut set computational framework is applied to evaluate the lethality of ribonucleotide reductase catalytic subunit M1 (RRM1) inhibition in multiple myeloma." (PMID 28878380, 2017). "This analysis predicted that ribonucleotide reductase catalytic subunit M1 (RRM1) is an essential gene in three of the four studied multiple myeloma cell lines, which could afterwards be validated in experiments." (PMID 40263955, 2025). "In the context of multiple myeloma, the expression of the HNRNPA2B1, USP1, RRM1, SPAG5, PCNA and TOP2A genes has been studied." (PMID 37048102, 2023). "To determine if the anti-myeloma activity of HDS depended on RRM2, we established stable RRM1- and RRM2-knockdown and overexpression MM cell lines." (PMID 35546402, 2022).
cervical cancer (6 papers, 2012 to 2023). A primary or metastatic malignant neoplasm involving the cervix. "In the risk model, LINC02535 has been shown that can enhance the stability of the downstream gene RRM1 by combining PCBP2 in cervical cancer." (PMID 33869203, 2021). "Cervical cancer cell lines were examined for the basal expression of hENT1, dCK, RRM1, RRM2, CDA genes and then their sensitivity to gemcitabine was evaluated." (PMID 22427797, 2012). "In addition, Wen and colleagues used cervical cancer cells to find that PCBP2 interacts with long non-coding RNA to stabilize RRM1 mRNA and promote epithelial mesenchymal transition and proliferation of cancer cells." (PMID 37814239, 2023).
Ewing sarcoma (6 papers, 2016 to 2025). A small round cell tumor that lacks morphologic, immunohistochemical, and electron microscopic evidence of neuroectodermal differentiation. "In this work, we identified that AP-1, in the setting of loss of RRM1 activity, downregulates the level of the c-Myc oncogene, which promotes tumorigenesis in Ewing sarcoma tumors via multiple pathways." (PMID 37599787, 2023). "In summary, we used a conditional knockout (CRISPR-Cas9) and rescue approach to target RRM1 and investigate the downstream signaling pathways activated by loss of this protein in Ewing sarcoma cells." (PMID 37599787, 2023). "In the current study, we used a conditional knockout (CRISPR/Cas9) and rescue approach to target RRM1 in Ewing sarcoma cells and identify downstream pathways impacted by the loss of RNR activity." (PMID 37599787, 2023). "Previously, we identified that HDAC inhibitors downregulate the RNR subunit RRM1 protein expression in Ewing sarcoma cells." (PMID 40478628, 2025). "In this work, we identify that HDAC inhibitors broadly disrupt DNA replication and the response to replication stress in Ewing sarcoma cells by downregulating RRM1, RRM2, CHK1, and WEE1." (PMID 40478628, 2025). "Treatment of the parental EW8 and TC71 cells, as well as additional Ewing sarcoma cell lines, with the RRM1 inhibitor gemcitabine also reduced the level of the c-Myc oncoprotein." (PMID 37599787, 2023). "Overall, these results support the conclusion that a reduction in RNR activity, mediated by either enzyme inhibition or reduction in RRM1/2 protein levels, results in activation of AP-1 signaling in Ewing sarcoma tumors." (PMID 37599787, 2023). "In this work, we identified that loss of RNR activity, via a conditional knockout approach targeting the RRM1 subunit of RNR, is sufficient to cause cell-cycle arrest, DNA damage, and apoptosis in Ewing sarcoma cells." (PMID 37599787, 2023). "We also showed that HDAC inhibitors, which reduce the level of the RRM1 protein, upregulate AP-1 and downregulate c-Myc in Ewing sarcoma cells." (PMID 37599787, 2023). "We previously identified, in unpublished work, that HDAC inhibitors decrease the level of the RRM1 protein in Ewing sarcoma and other cell types." (PMID 37599787, 2023). "In summary, we have identified that Ewing sarcoma cells are sensitive to gemcitabine, an irreversible inhibitor of RRM1." (PMID 29152060, 2017). "All four siRNAs in the pool showed effective knockdown of RRM1 and significant inhibition of Ewing sarcoma cell growth." (PMID 27557498, 2016). "We also used a set of siRNAs targeting RRM1 (si_RRM1_pool), the other subunit of RNR, to deplete RRM1 in Ewing sarcoma cells." (PMID 27557498, 2016). "Furthermore, we show that histone deacetylase (HDAC) inhibitors decrease the level of the RRM1 subunit in Ewing sarcoma cells, increase expression of c-Jun, and decrease the expression of c-Myc." (PMID 37599787, 2023). "Next, we generated a second Ewing sarcoma cell line (TC71) with conditional knockout of RRM1." (PMID 37599787, 2023). "In addition, small-molecule inhibitors of RNR, including gemcitabine, and histone deacetylase inhibitors, which reduce the level of the RRM1 protein, also activate AP-1 signaling and downregulate the level of c-Myc in Ewing sarcoma." (PMID 37599787, 2023). "In this study, we identified that multiple HDAC inhibitors, including fimepinostat, romidepsin, and panobinostat, downregulate the levels of the RRM1, RRM2, CHK1, and WEE1 proteins in Ewing sarcoma cells and impair DNA replication." (PMID 40478628, 2025). "In this study, we identify that HDAC inhibitors more broadly disrupt DNA replication and the cellular response to DNA replication stress by downregulating the expression of RRM1, RRM2, CHK1, and WEE1 in Ewing sarcoma cells." (PMID 40478628, 2025). "We used CRISPR/Cas9 to knockout RRM1, which is the catalytic subunit of RNR and the target of gemcitabine, in Ewing sarcoma cells." (PMID 37599787, 2023).
Ewing sarcoma (continued). "We and others have shown that Ewing sarcoma tumors are sensitive to small-molecule inhibitors of RNR, as well as knockdown of either the RRM1 or RRM2 subunit." (PMID 37599787, 2023). "Gemcitabine, on the other hand, is an irreversible inhibitor of the RRM1 subunit of RNR and this drug induces apoptosis in Ewing sarcoma cells when used in both 6-hour and longer drug treatments." (PMID 29152060, 2017). "Ewing sarcoma cells were also sensitive (IC50 range 2.4-10 nM) to gemcitabine, an inhibitor of RRM1." (PMID 27557498, 2016).
bladder cancer (5 papers, 2015 to 2021). "RRM1 is overexpressed in various types of cancers, including bladder cancer, and is associated with cell growth, migration, tumor development, and metastasis." (PMID 33921102, 2021). "Our study elucidates how RRM1 inhibition affects cancer cell proliferation and influences gemcitabine-resistant bladder cancer cells." (PMID 33921102, 2021). "Cancer gene therapy using anti-RRM1 shRNA has pronounced antitumor effects against RRM1 highly expressed tumors, and RRM1 inhibition specifically increases bladder cancer cell GEM-sensitivity." (PMID 33921102, 2021). "In the present study, we further explored the potential of Ad-shRRM1, this time in bladder cancer cells and found that Ad-shRRM1 effectively downregulated RRM1 expression, resulting in suppression of bladder cancer cell proliferation in vitro and in vivo." (PMID 33921102, 2021). "Ad-shRNA knockdown strongly inhibited the viability of RRM1-expressing bladder cancer cells, 253J and RT112." (PMID 33921102, 2021). "RRM1 gene expression varied from 28.6% (T24) to 153.5% (J82) (median: 116.9%) in bladder cancer cells." (PMID 33921102, 2021). "Several clinical studies have confirmed the relationship between high expression of RRM1 and adverse clinical outcomes in patients with advanced bladder cancer." (PMID 33921102, 2021). "Of nine bladder cancer cell lines investigated, two RRM1 highly expressed cells, 253J and RT112, were selected for further experimentation." (PMID 33921102, 2021). "The expression level of ribonucleotide reductase subunit M1 (RRM1) is closely related to the effect of gemcitabine-based therapy in advanced bladder cancer." (PMID 31340801, 2019). "In this study, a gemcitabine-resistant human bladder cancer cell line was established, and the role of RRM1 and RRM2 in the development of gemcitabine resistance was initially investigated." (PMID 26658059, 2015). "Even though Ad-shRRM1 in itself showed potent inhibitory effects on cell proliferation, combination treatment with Ad-shRRM1 and GEM reduced the 50% inhibitory concentration (IC50) of GEM to a greater extent, in both of the RRM1 highly expressed bladder cancer cells." (PMID 33921102, 2021). "Combination therapy with Ad-shRRM1 and GEM specifically induces a synergistic cytotoxicity in RRM1-expressing bladder cancer cells and could achieve the same effect with a reduced dosage of either one of the individual drugs." (PMID 33921102, 2021). "Our data suggested that RRM1 and RRM2 overexpression could be associated with the progression of bladder cancer." (PMID 26658059, 2015). "Therefore, inhibiting RRM1 may become a new treatment strategy in patients with bladder cancer, not only to inhibit cell viability but also to reduce GEM-resistance." (PMID 33921102, 2021). "We elucidated the potential of Ad-shRRM1 as a therapeutic agent for bladder cancer and demonstrated that Ad-shRRM1 inhibits bladder cancer cell viability and enhances GEM-sensitivity, by reducing RRM1 expression." (PMID 33921102, 2021). "Our study found that RRM1 and RRM2 were expressed in clinical bladder cancer tissues and bladder cancer cell lines." (PMID 26658059, 2015). "In bladder cancer cell lines, RT-PCR results demonstrated that RT112-Gr cells had significantly increased in the levels of RRM1 and RRM2 mRNA compared with the parental cells(p<0.001), respectively." (PMID 26658059, 2015). "Our present study indicates that RRM1 and RRM2 are involved in gemcitabine resistance in human bladder cancer." (PMID 26658059, 2015). "Immunohistochemical analysis was performed to assay RRM1 and RRM2 expression in surgically resected specimens of bladder cancer." (PMID 26658059, 2015). "RT112-Gr cells were left untreated or were treated with 45nM Gemcitabine (GEM), RNAi-mediated Knockdown of RRM1 and RRM2 in RT112-Gr bladder cancer cells were left untreated or were treated with 45nM Gemcitabine (GEM)." (PMID 26658059, 2015).
bladder cancer (continued). "However, there is limited information concerning RRM1 and RRM2 protein expression in bladder cancer, and to our knowledge no reports exist describing the role of RRM in the process of drug resistance in bladder cancer." (PMID 26658059, 2015). "RRM1 and RRM2 gene expression might be a predictive marker for the efficacy of gemcitabine therapy in bladder cancer patients." (PMID 26658059, 2015). "This is the first report of RRM1 and RRM2 protein overexpression in bladder cancer." (PMID 26658059, 2015). "Our study indicated that after knockdown of RRM1/2, RT112-Gr bladder cancer cell lines sensitive to gemcitabine again, indicating the overexpression of RRM was associated with gemcitabine resistance, and might be a novel candidate biomarker for gemcitabine resistance." (PMID 26658059, 2015).
gastric cancer (5 papers, 2013 to 2019). A primary or metastatic malignant neoplasm involving the stomach. "Therefore, the present study was to investigate whether the genes ERCC1, BRCA1, TYMS, RRM1, TUBB3, STMN1 and TOP2A are underlying biomarkers for patients with gastric cancer, which, to our knowledge, has not been performed." (PMID 28056823, 2017).
glioblastoma (5 papers, 2021 to 2024). The most malignant astrocytic tumor (WHO grade IV). "Among the enzymes associated with nucleotide synthesis, RRM1 and NME1 are significantly upregulated in glioblastoma." (PMID 36175487, 2022). "We showed that RRM1 and NME1 were significantly upregulated in both pyrimidine and purine synthesis pathways in glioblastoma, elevated more than twofold compared to near-normal brain, suggesting that these enzymes might offer therapeutic targets for the treatment of glioblastoma." (PMID 36175487, 2022).
leukemia (5 papers, 2018 to 2026). A malignant (clonal) hematologic disorder, involving hematopoietic stem cells and characterized by the presence of primitive or atypical myeloid or lymphoid cells in the bone marrow and the blood. "Thus, while the median survival of mice with leukemia driven by BCR-ABL/MSI2-HOXA9ΔHOXA9 (BCR-ABL/ΔHOXA9) was 26 days, the loss of RRM1 led to a median survival of 46 days, similar to BCR-ABL alone (43.5 days)." (PMID 41498402, 2026). "Thus, while the median survival of mice with leukemia driven by BCR-ABL/∆HOXA9 was 26 days, the loss of RRM1 (BCR-ABL/∆RRM1) was 46 days, similar to BCR-ABL alone (43.5 days)." (PMID 38234720, 2023). "In addition, higher RRM1 expression in leukemia blast cells predicts better relapse-free survival (RFS) in AML patients." (PMID 29631596, 2018). "An inverse correlation between RRM1/RRM2 mRNA expression and intracellular ara-CTP in leukemia blasts after Ara-C treatment is observed in clinic." (PMID 29631596, 2018). "Therefore, we performed additional in vitro experiments based on the two best 5-protein models (which shared TYMP, RRM1, UPP1, and UCK1 and contained either PPAT or UCK2) using two CRC and two leukemia cell lines that are predicted to be sensitive or resistant to 5FU." (PMID 32686665, 2020).
melanoma (5 papers, 2012 to 2025). A malignant, usually aggressive tumor composed of atypical, neoplastic melanocytes. "Taken together, our data indicate that depletion of dNTPs is one of the major causes of DNA damage and senescence in MYC-depleted melanoma cells and that maintaining high TS, RRM1 and RRM2 levels is important for C-MYC-dependent suppression of senescence programs in these cells." (PMID 23249808, 2012). "Mechanistically, MTCH2 enhanced the expression and nuclear translocation of nuclear factor (erythroid-derived-2)-like 2 (NRF2), which up-regulated ribonucleotide reductase subunit M1 (RRM1) expression, thereby promoting melanoma cell proliferation." (PMID 40204724, 2025). "MTCH2 appears to enhance the expression and nuclear translocation of NRF2, which in turn increases RRM1 expression and promotes melanoma cell proliferation." (PMID 41227324, 2025). "Among them, TXNRD1 is targeted by arsenic trioxide and fotemustine (approved in some countries against melanoma brain metastasis), and RRM1-2 by seven antimetabolites." (PMID 38701414, 2024). "Therefore, co-expression of TS, RRM1 and RRM2 in melanoma cells partially overcomes senescence caused by C-MYC depletion." (PMID 23249808, 2012).
pancreatic adenocarcinoma (5 papers, 2012 to 2021). "Deoxycytidylate deaminase (DCTD) and ribonucleotide reductase subunit M1 (RRM1) are potential prognostic and predictive biomarkers for pyrimidine-based chemotherapy in pancreatic adenocarcinoma." (PMID 29523831, 2018). "For validation experiments, we focused our efforts on CENPE and RRM1 because of their biological significance in pancreatic adenocarcinoma and the availability of validated small molecule inhibitors." (PMID 30323222, 2018). "Expression of either DCTD or RRM1 was not prognostic or predictive in patients with pancreatic adenocarcinoma who had had post-operative chemotherapy with either gemcitabine or 5-fluorouracil with folinic acid." (PMID 29523831, 2018).
squamous cell carcinoma (5 papers, 2007 to 2015). A carcinoma arising from squamous epithelial cells. "For expression levels by histology, we found that squamous cell carcinomas tended to have higher levels of both RRM1 (p < 10–5) and RRM2 (p < 10–5 cytoplasmic and nuclear) than adenocarcinomas." (PMID 26001082, 2015). "We investigated the relationship between peripheral blood RRM1, ERCC1, and BRCA1 expression levels with histopathology classifications (squamous cell carcinoma, adenocarcinoma), smoking, age, clinical staging (IIIB and IV), and chemotherapy response." (PMID 24591771, 2014).
glioma (4 papers, 2020 to 2024). A benign or malignant brain and spinal cord tumor that arises from glial cells (astrocytes, oligodendrocytes, ependymal cells). "miR-1468-5p has previously been associated with glioma, where it inhibits growth and cell cycle progression by targeting ribonucleotide reductase large subunit M1 (RRM1), based on a study on patients from the Chinese Glioma Genome Atlas." (PMID 32512929, 2020). "RRM1-2 showed higher dependency probability (the likelihood that the KO of a gene reduces cell growth or induces cell death) than AntiBCs’ targets in the glioma cell lines." (PMID 38701414, 2024). "In glioma however, RRM1 appears to be a tumour-promoting factor, as RRM1 silencing induced cell cycle arrest and inhibited the proliferation of the tumour cells." (PMID 38672281, 2024). "MiR-1468-5p by targeting RRM1 could inhibit glioma cell proliferation and induce G1/S arrest." (PMID 33330110, 2020).
lung adenocarcinoma (4 papers, 2008 to 2026). A carcinoma that arises from the lung and is characterized by the presence of malignant glandular epithelial cells. "In conclusion, the results of the present study revealed that the efficacy of docetaxel/gemcitabine in lung adenocarcinoma patients is associated with RRM1 and RRM2 mRNA expression, thus indicating the importance of tailoring treatment." (PMID 18414411, 2008). "For RRM1, some studies showed that high RRM1 expression was associated with better survival in early stage NSCLC or had poor prognosis in advanced NSCLC or lung adenocarcinoma, while another study showed that RRM1 protein expression had no significant predictive value for early NSCLC patients." (PMID 31637211, 2019). "Previously, one study investigated the mRNA expression of RRM1 and RRM2 in tumors from patients with lung adenocarcinoma treated with docetaxel/gemcitabine." (PMID 40258059, 2025). "The mRNA expression of RRM1 and RRM2 in tumours from lung adenocarcinoma patients treated with docetaxel/gemcitabine was assessed and the results correlated with clinical outcome." (PMID 18414411, 2008). "To further investigate this issue, we have carried out a multicentre phase II study to evaluate the impact of RRM1 and RRM2 mRNA expression in the tumours of lung adenocarcinoma patients treated with docetaxel/gemcitabine." (PMID 18414411, 2008).
ovarian carcinoma (4 papers, 2014 to 2025). A malignant neoplasm originating from the surface ovarian epithelium. "The strongest links were observed between TYMS, RRM1, and DNA metabolic process-related terms, underscoring their role in proliferation and genomic maintenance in ovarian cancer." (PMID 41009727, 2025).